TNF (tumor necrosis factor)
Diseases named in the same sentence as TNF in open-access papers (continued):
Sharing a sentence is not in itself a finding about the gene and the disease.
breast carcinoma (continued). "A few days in the diagnosis, breast cancer subjects had significantly higher systolic blood pressure (p = 0.03), glucose (p = 0.01), triglycerides (p = 0.001), leptin (p = 0.044), resistin (p = 0.04), ANG II (p = 0.02), TNF-α (p = 0.045), and CRP (p = 0.04) than the controls." (PMID 23374911, 2013). "Although CD8+CTLs stimulated with MGBA protein-pulsed DCs could efficiently lyse MDA-MB 415 cells, CD8+CTLs stimulated by Ad-MGBA infected DCs with or without added TNF-α had better cytotoxic activity against breast cancer cells compared to the others." (PMID 23650543, 2013). "For example, breast cancer patients with elevated levels of COX2 and PGE2 within the tumor and the circulation presented T cells with decreased proliferation in response to CD3 antibody stimulation, reduced levels of TNF-α, interleukin (IL)-12, IL-2, and increased levels of IL-10 and IL-4." (PMID 23029485, 2012). "Within human breast cancer cell lines, expressions of TRF1, TIN2, and POT1 are upregulated by dexamethasone, suggesting activation of the glucocorticoid receptor, whereas TERT, TRF2, TRF1, TIN2, and POT1 are upregulated by TNF-α, suggesting activation of the NFκB transcription factor." (PMID 23342266, 2012). "In summary, the obtained results showed that D-glucuronyl C5-epimerase significantly suppress proliferative activity of breast cancer cells in vitro through the activation of tumour suppressor genes р53, BRCA1, SYK and E2F1 and change of a balance of pro- and apoptotic factors BCL2, NFKB1 and TNF." (PMID 20723247, 2010). "Our study further found that ABL-N induced significant activation of caspase-8 in the breast cancer cells, suggesting that ABL-N may activate the death receptor pathway and induce the expression of death receptors or death ligands such as tumor necrosis factor-α and Fas ligand." (PMID 20096139, 2010). "The obtained data indicated that antimitotic effect of D-glucuronyl C5-epimerase in human breast cancer cells in vitro probably is realized mainly via the activation of tumour suppressor genes р53, BRCA1, SYK and E2F1 and change of a balance of pro- and anti-apoptotic factors BCL2, NFKB1 and TNF." (PMID 20723247, 2010). "Our proteomic analysis of two MCF-7 human breast cancer cell lines revealed at least seven differentially expressed protein spots in two-dimensional gels, which may contribute to the mechanisms of MEK5/Erk5-mediated TNF-α resistance." (PMID 19087274, 2008). "Importantly, TNF-α has been shown to increase the subpopulation of breast cancer stem-like cells: via non-canonical NF-κB, TNF-α upregulates TAZ, a transcriptional co-activator in the Hippo pathway, thereby enriching tumor-initiating cells that drive recurrence and chemotherapy resistance." (PMID 41007766, 2025). "For example, in breast cancer (BC), tumor necrosis factor–α (TNF-α)–induced protein-8 like-2 (TIPE2) fosters the production of interferon-γ (IFN-γ) and TNF-α by NK cells, enhances the killing ability of NK cells to BC cells, and hampers the development and metastasis of BC." (PMID 38073330, 2024). "Although immunomodulatory effects of honey in the duodenum are unknown, in rat models of breast cancer, Tualang and manuka honey reduced TNF-α expression, while in a neuroinflammation model, Tualang honey reduced neuroinflammation with a considerable decrease in IL-β and TNF-α." (PMID 38045104, 2023). "Furthermore, the combination of butyrate with tumor necrosis factor-α (TNF-α), tumor necrosis factor-related apoptosis-inducing ligand (TRAIL), and anti-Fas agonist has been found to strongly induce apoptosis, leading to a significant decrease in the viability of breast cancer cells." (PMID 37764768, 2023). "Moreover, oncogenic miR-183-5p in breast cancer-derived EVs are engulfed by macrophages and downregulate target gene PPP2CA expression by combining with the binding sequence which leads to a decrease in dephosphorylation of p65, consequently promoting IL-1β, IL-6, and TNF-α secretion." (PMID 36405712, 2022).
breast carcinoma (continued). "There are reports that chronic stress could induce a microenvironment with an enhanced expression of inflammatory factors, such as TNF-α, IL-1, IL-6, and IL-8, which are believed to play a role in malignant tumor progression and negative prognosis in cancers, including breast cancer." (PMID 34485118, 2021). "Hence, it is plausible that the elevated TNF-α partially accounts for the induction and overexpression of MAT2A in breast cancer, and there could be a link between inflammation and MAT2A expression during breast cancer progression." (PMID 34065390, 2021). "Moreover, targeting STAT3 in human breast cancer cells was reported to suppress the tumor progression by regulating the expression of crucial proteins in tumor milieu, such as survivin, chemokines (CCL5 and CXCL10) and proinflammatory cytokines (IL-6, IL-5, TNF-a, and IFN-γ)." (PMID 33957948, 2021). "Moreover, TNFα signalling combined with RAS hyperactivity may promote tumorigenesis-enabling inflammation in a positive feedback loop that favours cell survival over apoptosis, which has been described in colorectal carcinoma and breast cancer." (PMID 33138083, 2020). "The finding that TNF-α could induce fusion via an MMP9-dependent mechanism is further supported by data showing that the fusion of osteoclasts in bone explants, which were stimulated by human breast cancer cells through TNF-α secretion, could be blocked by the inhibition of MMP9." (PMID 29636110, 2018). "To further validate that the macrophoages/TNFα could activate YAP and HK2 in vivo, we evaluated the relevance of CD68+ (highly expressed in blood monocytes and tissue macrophages) staining with YAP or HK2 staining in human breast cancer samples via immunohistochemical staining." (PMID 28945218, 2017). "Nevertheless, in the context of breast cancer, clinical studies have suggested that the use of TNFis to block TNF-α signaling, rather than reducing inflammation may increase the risk of malignancy by promoting invasiveness and tumor growth, which deserves further investigation." (PMID 29202842, 2017). "Thus, ATR-II abated proinflammatory cytokines (TNF-α and IL-6), reduced oxidative markers (MDA and 8-OH-dG) and increased GSH/GSSG ratio in the mammary glands, which suggested that ATR-II had anti-inflammatory and antioxidant activities in the NMU-induced rat breast cancer model." (PMID 29100404, 2017). "However, the role of TNF-α in the development of breast cancer is not well documented." (PMID 28938560, 2017). "PTX3 silencing in MDA-MB-231 cells transfected with PTX3 siRNA significantly decreased TNF-α-mediated RANKL production in the co-culture system, but did not modulate OPG production, supporting the notion that PTX3 may serve as an inflammatory mediator involved in breast cancer-related osteolysis." (PMID 24457902, 2014). "The tumor-promoting activities of the inflammatory mediators CCL2 & CCL5 and TNFα & IL-1β in breast cancer are not fully overlapping (references above), therefore their coordinated expression may eventually provide advantage to the developing and metastasizing tumor." (PMID 21486440, 2011). "Therefore IL-17 does not appear to act by inducing TNFα production from breast tumour cells, and as such may represent an additional pathway involved in the spread of breast cancer." (PMID 19014637, 2008). "Third, the robust neutrophil recruitment activity of aggressive breast cancer cell lines, for example, M4, MDA-MB-231, and BT549, is not further amplified by TGF-β1/TNF-α treatment, even though the latter enhances expression of key EMT markers." (PMID 40833805, 2025). "This study, through a systematic review and meta-analysis, examined the outcomes of 19 articles that classified breast cancer based on the presence or absence of specific biomarkers (ER, PR, HER2, IL-6, TNF-alpha)." (PMID 40558287, 2025).
breast carcinoma (continued). "We first used the nonmalignant MCF10A cells, the M1 cells in the breast cancer progression model to investigate the effect of TGF-β1/TNF-α treatment on their neutrophil recruitment ability." (PMID 40833805, 2025). "Serum levels of EGF, G-CSF, TNFα, Groα, IP10, MIP-1b, MDC, VEGFα, TGFβ1, and TGFβ2 were also high in women with breast cancer compared to the control group (no cancers)." (PMID 38541912, 2024). "Other data demonstrated that NF-κB is required for the dex-related protective effect against TNF-α-mediated cell death and correlated with lack of degradation of the anti-apoptotic protein c-IAPI in breast cancer cells." (PMID 35761157, 2022). "Azilsartan significantly (p < 0.001) decreased NF-kB protein levels in non-stimulated and 20 ng/mL TNFα-stimulated MCF-7 and MDA-MB-231 breast cancer cells." (PMID 36431925, 2022). "We then found that HMMR expression is positively correlated with the “TNF signaling via NF-κB” and “KEGG cytosolic DNA sensing” pathways in human basal-like and/or claudin-low tumors, but not in the other major breast cancer subtypes." (PMID 35393420, 2022). "Considering the lack of knowledge, feline serum VISTA levels from cats with mammary carcinoma were compared with healthy controls, and with serum levels of PD-1/PD-L1, CTLA-4, LAG-3, IL-6, and TNF-α." (PMID 34771722, 2021). "In this study, we demonstrate that TNF-α increases BCSCs in MCF7 and MDA-MB-468 breast cancer cell lines through induction of TAZ (but not YAP) transcription." (PMID 32019974, 2020). "This study aimed to investigate cytokine mRNA expression levels of IL-6, IL-18, TNF-α, and CRP in hepatocytes from breast cancer xenograft mice with or without moderate exercise." (PMID 32309219, 2020). "TNF stimulates the growth of normal mammary epithelial cells and the mammary cancer cells; thus we studied the effects of TNF-α on the proliferation, migration, and EMT of breast cancer cells with or without OA." (PMID 31341911, 2019). "Although evidence in the literature show butein potential in protecting against and suppressing cancer, there are no studies to compare the effect of this compound on TNF-α-induced CCL2 release in Caucasian and African American breast cancer cell lines." (PMID 31665136, 2019). "Since IFN-γ/TNF-α treatment of patients is not advisable, HER2+ breast cancer patients were treated with HER2-pulsed dendritic cells (DC) to restore depressed Th1 response which seems to be due to a functional and reversible cytokine shift." (PMID 29725336, 2018). "While studying the transcriptional regulation of iNOS in breast cancer cell lines, we noticed that in general lines such as MCF-7 express the enzyme in response to stimulation with a cytokine mix (Il1-β, IFN-γ and TNF-α) while others such as MDA-MB-231 do not." (PMID 26271992, 2015). "Although cytokines such as TNF-α, TGF-1, IL-6, and IL-1β are capable of inducing EMT in breast cancer cells, the source of these factors has not been studied." (PMID 26207636, 2015). "However, TNF was shown to induce EMT and to create a permissive environment for a “non-CSC to CSC” conversion in breast cancer, and our data do not exclude the possibility that this mechanism could be responsible for the TNF-induced changes in the melanoma SC compartment." (PMID 25223735, 2014). "In this study, TNFα treatment led to significant over-expression of PTX3 in bone metastatic breast cancer cells, but not in non-bone metastatic breast cancer cells, reinforcing PTX3 as a modulator of breast cancer-related inflammation." (PMID 24457902, 2014). "In this study, we focused on roles of KSG-002 in breast cancer cells, especially highly metastatic breast cancer cells, and found that the combination of KSG-002 with TNFα reduced MDA-MB-231 cell viability, while KSG-002 or TNFα alone did not affect it." (PMID 23818931, 2013). "However, trastuzumab could not inhibit TNFα ability to promote breast cancer growth." (PMID 22295219, 2011).
breast carcinoma (continued). "Next, we compared the three groups of breast cancer patients (DCIS, IDC-no-relapse, IDC-with-relapse) with respect to the incidence of expression of CCL2, CCL5, TNFα and IL-1β in the tumor cells." (PMID 21486440, 2011). "To find out if this was indeed the case, we determined in each of the three groups of breast cancer patients (DCIS, IDC-no-relapse, IDC-with-relapse) the parameters of % TNFα-positive cells in the tumors, and the score of TNFα expression." (PMID 21486440, 2011). "Additionally, the relationship between TNF-α resistance mediated by MEK5/Erk5 signaling and epithelial-mesenchymal transition (EMT), a process associated with promotion of invasion, metastasis, and recurrence in breast cancer, has not previously been investigated." (PMID 19087274, 2008). "Using the ERα-negative breast cancer cell line MDA-MB-231 stably overexpressing ERα, we show that ERα transrepresses tumour necrosis factor alpha (TNFα)-inducible expression of IL-6." (PMID 14970864, 2004). "Also, in breast cancer cells, the dual SOD/catalase mimetic EUK-134—but not an SOD-only mimic—clears both superoxide and H2O2 to inhibit TNF-α–induced NF-κB activation, suppress tumorigenic behaviors, and induce cell-cycle arrest and apoptosis." (PMID 41009046, 2025). "Collectively, these data show that in breast cancer patients, circulating NKT cell number may not correlate with function and provide a subset of biomarkers TNF-α, LAG3, and LIGHT, which can be used to assess immune function." (PMID 39596374, 2024). "For women with breast cancer, IL6 (b = 2.469, 95% CI [− 7.614, 12.552], p = 0.631) and TNFα (b = 0.036, 95% CI [− 6.345, 6.418], p = 0.991) were not statistically significant moderators of the effect of exercise intensity on changes in muscle strength (Model 1.2)." (PMID 36658635, 2023). "We assessed the mRNA expression of resistin, tumor necrosis factor-alpha (TNF-α), interleukins 6 and 8 (IL-6, and IL-8), and estrogen receptor alpha (ER-α) in peripheral blood mononuclear cells (PBMCs) of women with and without breast cancer." (PMID 33517609, 2021). "TAZ is induced by TNF-α through the non-canonical NF-κB pathway, and our findings suggest that TAZ plays a crucial role in inflammatory factor–promoted breast cancer stemness and could serve as a promising therapeutic target." (PMID 32019974, 2020). "Interestingly, only the non-metastatic triple-negative MDA-MB-468 breast cancer cell conditioned media had a negative effect on both IL10 and TNFα expression in monocytes." (PMID 31105883, 2019). "Moreover, a correlation was found between the expression levels of WWP1 in four breast cancer cell lines and TRAIL resistance, but not tumor necrosis factor alpha (TNFα) and doxorubicin resistance." (PMID 30619734, 2018). "In the present study, we observed that patients whose CD8+ T-cells produced TNF had a significant survival advantage over those who did not, indicating the importance of Her-2-reactive TNF-producing CD8+ T-cells for these elderly breast cancer patients." (PMID 26500775, 2015). "In flow cytometry, cocultures of the breast cancer cell lines HS578T_pDFR.2 and MDA-MB-435S_pFDR.1 with M13SV1_miCP wild-type or M13SV1_ASCT2KO_ miCP cells yielded low amounts of green fluorescent cells beneath 0.1%, which were not significantly altered by addition of TNFα." (PMID 38891857, 2024). "Indeed, non-aggressive MCF-7 and aggressive MDA-MB-231 breast cancer cells show diverse tumor behaviors in response to TNF-α, including cancer cell proliferation and migration to the TNF-α-induced tumor response due to discrepancies in TNF-α-mediated NF-κB activation." (PMID 33816268, 2021). "To further examine the effects of TNF-α on the aggressiveness levels of breast cancer cells in our present analyses, we compared the cell growth rates and migratory capacity of the non-aggressive MCF-7 and aggressive MDA-MB231 breast cancer cell lines following exposure to this cytokine (20 ng/ml)." (PMID 33816268, 2021).
breast carcinoma (continued). "To investigate the relevance of TNF signaling via NFκB activation and NCS1 up‐regulation in human cancer, we analyzed the gene expression patterns of NFκB‐regulated genes and NCS1 expression in a dataset from an RNA microarray performed on human breast cancer and noncancerous breast tissue." (PMID 32239615, 2020). "After verifying that MK-2206 plus IFN-gamma could show similar combined effects against breast cancer lines, even in the absence of TNF-alpha, we tested in a rodent HER-2pos breast cancer model either a HER-2-based DC vaccine, or recombinant IFN-gamma with or without MK-2206 administration." (PMID 32774769, 2020). "We also found that TNF-α upregulated the expression of the dipeptidyl peptidases CD26 and FAP-α in a dose-dependent manner and, in addition, enhanced the concentration of all five proteases in lipid rafts in the breast cancer-derived cells tested, regardless of cell type." (PMID 27042827, 2016).